SLC25A29 (solute carrier family 25 member 29)
Description:
Mitochondrial transporter of arginine, lysine, homoarginine, methylarginine and, to a much lesser extent, ornithine and histidine. Does not transport carnitine nor acylcarnitines. Functions by both counter-exchange and uniport mechanisms. Plays a physiological role in the import of basic amino acids into mitochondria for mitochondrial protein synthesis and amino acid degradation.
Synonyms: C14orf69; ORNT3; FLJ38975; CACL
Tractability: Antibody: UniProt predicts a signal peptide or a membrane-spanning region. PROTAC: ubiquitination databases record sites on it; its protein half-life has been measured.
Gene: Protein-coding gene on chromosome 14 (100,291,116 to 100,306,547, reverse strand). Ensembl gene ENSG00000197119.
Subcellular location: Mitochondrion inner membrane
Pathways (Reactome):
Transport of small molecules: Amino acid transport across the plasma membrane
Gene Ontology:
Molecular function: arginine:ornithine antiporter activity; basic amino acid transmembrane transporter activity; high-affinity L-arginine transmembrane transporter activity; high-affinity lysine transmembrane transporter activity; L-lysine:L-arginine antiporter activity; O-acyl-L-carnitine transmembrane transporter activity
Biological process: carnitine transport; L-arginine transmembrane transport; L-histidine transmembrane transport; L-lysine transmembrane transport; mitochondrial L-ornithine transmembrane transport; O-acyl-L-carnitine transmembrane transport; ornithine transport; amino acid transport; transmembrane transport
Cellular component: mitochondrial inner membrane; mitochondrion
Genetic constraint (gnomAD): Loss-of-function variants: 13 observed, 9.89 expected, observed/expected ratio (o/e) 1.31, 90% interval 0.85 to 1.87. That is too few expected variants to judge how well the gene tolerates losing a copy. Missense variants: 475 observed, 384.35 expected, observed/expected ratio (o/e) 1.24, 90% interval 1.15 to 1.33. Synonymous variants: 244 observed, 182.71 expected, observed/expected ratio (o/e) 1.34, 90% interval 1.2 to 1.49.
Homologues: Orthologues: chimpanzee SLC25A29 (99% identical), macaque SLC25A29 (98% identical), mouse Slc25a29 (89% identical), dog SLC25A29 (88% identical), rat Slc25a29 (88% identical), rabbit SLC25A29 (82% identical), guinea pig SLC25A29 (76% identical), tropical clawed frog slc25a29 (73% identical), zebrafish slc25a29 (73% identical), zebrafish SLC25A29 (71% identical), Drosophila melanogaster CG4995 (45% identical), Caenorhabditis elegans slc-25A29 (45% identical). Paralogues in human: SLC25A45 (39% identical), SLC25A48 (37% identical), SLC25A47 (37% identical), SLC25A20 (36% identical), SLC25A13 (31% identical), SLC25A12 (31% identical), SLC25A15 (31% identical), SLC25A2 (30% identical), SLC25A39 (28% identical), SLC25A23 (27% identical), SLC25A31 (27% identical), SLC25A25 (26% identical), and 37 more.
Diseases named in the same sentence as SLC25A29 in open-access papers:
SLC25A29 is named in the same sentence as 12 diseases in open-access papers, as found by Europe PMC text mining. Sharing a sentence is not in itself a finding about the gene and the disease. The quoted sentences say what the papers report.
lung adenocarcinoma (4 papers, 2023 to 2025). A carcinoma that arises from the lung and is characterized by the presence of malignant glandular epithelial cells. "In lung adenocarcinoma, elevated levels of lactylation of Solute Carrier Family 25 Member 29 (SLC25A29) limit its transcription, and low expression of SLC25A29 is associated with angiogenesis in endothelial cells." (PMID 40057816, 2025). "In lung adenocarcinoma endothelial cells, H3K18la and H3K14la reduce the expression of solute carrier family 25 member 29 (SLC25A29), and low SLC25A29 expression is associated with LUAD progression." (PMID 39026681, 2024). "Another study found that elevated histone lactylation levels in lung adenocarcinoma cells significantly reduced the expression of the solute carrier family 25 member 29 (SLC25A29) gene, promoting lung adenocarcinoma cell proliferation and migration." (PMID 40443721, 2025).
cardiomyopathy (1 paper, 2018). A disease of the heart muscle or myocardium proper. "The Slc25a29 gene codes for a mitochondrial carrier, palmitoylcarnitine transporter, the clinical consequences of its alteration may lead to hypoglycaemia, hyperammonaemia, cardiomyopathy, liver failure, and encephalopathy." (PMID 30537945, 2018).
cancer (7 papers, 2016 to 2024). A tumor composed of atypical neoplastic, often pleomorphic cells that invade other tissues. "In summary, SLC25A29 is dysregulated in cancer, and its expression favors tumor progression and angiogenesis." (PMID 39795950, 2024). "In cancer, SLC25A29 is upregulated in human cell lines of cervical and prostate cancers, as well as in HCC and PDAC." (PMID 39795950, 2024). "Taken together, this suggests that cancer cells upregulate SLC25A29 expression as a mechanism to sustain redox homeostasis and reprogram metabolism toward aerobic glycolysis, while reducing OXPHOS." (PMID 39795950, 2024). "Mitochondria-derived nitric oxide is known to have a dichotomous role in regulation of cancer progression which is influenced by expression of SLC25A29 likely affecting disease outcome." (PMID 36845715, 2023). "Intriguingly, SLC25A11 and SLC25A29 have also been reported to be involved in cancer progression by affecting mitochondrial function." (PMID 37550282, 2023). "The knockdown of SLC25A29 in cancer cells led to a reduction in mitochondrial-derived NO, which resulted in enhanced mitochondrial respiration and reduced glycolysis, thereby reversing the metabolic process." (PMID 36514121, 2022). "We identified other genes (SLC22A24, SLC25A29 and FREM1) as associated with EMT; they were linked to cancer for the first time." (PMID 27549611, 2016). "So far, we could only find one study related to the role of SLC25A29 in cancer in the Pubmed database." (PMID 37775731, 2023). "This study may provide some preliminary information, but further research is necessary to comprehensively understand the function and potential impact of SLC25A29 in cancer." (PMID 37775731, 2023). "However, specific research available on SLC25A29 is limited, and its involvement in cancer has not been extensively studied." (PMID 37775731, 2023).
tumor (6 papers, 2016 to 2024). "The downregulation of SLC25A29 appears to be mediated by increased histone lactylation of its gene promoter, representing an example of the cross-talk between tumor cells and the tumor microenvironment." (PMID 39795950, 2024). "The downregulation of SLC25A29 in tumor tissue was demonstrated in three pairs of patients with LUAD protein samples." (PMID 37775731, 2023). "To understand the reasons for the decreased expression of SLC25A29 in the tumor microenvironment, we attempted to find some clues from 515 RNA-seq data in the TCGA database." (PMID 37775731, 2023). "Tumor immune analysis revealed that SLC25A11 and SLC25A29 are involved in opposing tumor immunity together." (PMID 36514121, 2022). "In our study, CDH1 was one of seven EMT-associated genes (CDH1, SCD, PAPSS2, C3orf52, FREM, SLC22A24, SLC25A29) successfully validated to be deregulated in tumor tissue." (PMID 27549611, 2016). "Notably, SLC25A29 is downregulated in endothelial cells within the lung adenocarcinoma tumor microenvironment." (PMID 39795950, 2024). "In this study, the downregulation of SLC25A29 in tumor tissue and its lower expression in endothelial cells in LUAD tissues compared with adjacent normal tissues were confirmed through various experiments, including RT-qPCR, western blotting, and immunohistochemistry." (PMID 37775731, 2023). "Notably, SLC2A1, SLC25A29, and SLC27A4 were identified as key genes associated with survival and tumor stage." (PMID 37775731, 2023). "In addition, a set of enzymes responsible for carnitine shuttling, which are encoded by SLC22A1, SLC25A20, SLC25A29, and CPT2, are downregulated in HCC tumor cells." (PMID 33424926, 2020). "Upregulation of SLC25A29 may increase the concentration of arginine in the mitochondrial matrix, which is then utilized by mitochondrial arginase 2 to produce ornithine; the latter serves as a precursor for polyamine synthesis, metabolites known for their tumor-promoting properties." (PMID 39795950, 2024). "The correlation between SLC25A11, SLC25A29, and SLC25A44 mRNA expression levels and tumor immune invasion was further explored in PC." (PMID 36514121, 2022). "SLC25A members are crucial for tumor immune and energy metabolism in PC, and SLC25A11, SLC25A29, and SLC25A44 can be used as favorable prognostic markers." (PMID 36514121, 2022). "According to co-expression network studies, SLC25A11, SLC25A29, and SLC25A44 were involved in the energy metabolism of PC and prevented tumor growth, invasion, and metastasis." (PMID 36514121, 2022). "Interestingly, SLC25A11, SLC25A29, and SLC25A44 were significantly overexpressed in ductal, acinar and endocrine cells in tumor tissues compared with normal tissues (P < 0.001)." (PMID 36514121, 2022).
inherited metabolic disorders (1 paper, 2023). "Most studies on SLC25A29 have focused on its role in inherited metabolic disorders." (PMID 37775731, 2023).
SLC25A29 also shares sentences with these, for which no sentence is quoted: atherosclerosis (1 paper); Encephalopathy (1); Hyperammonemia (1); hypoglycaemia (1); liver failure (1); metabolic syndrome (1); pituitary adenomas (1).